COL3A1 (collagen type III alpha 1 chain)
Diseases named in the same sentence as COL3A1 in open-access papers (continued):
Sharing a sentence is not in itself a finding about the gene and the disease.
glioblastoma (11 papers, 2016 to 2025). The most malignant astrocytic tumor (WHO grade IV). "Similarly, COL3A1 has been implicated in the progression of hepatocellular carcinoma and glioblastoma, with its overexpression correlating with poor prognosis and enhanced tumor aggressiveness." (PMID 40087784, 2025). "TME rearrangements in OS have been correlated with chemotherapy-resistant phenotypes, whereas a survival gene signature based on the expression of collagen genes Col3a1, Col4a1, and Col5a2 is correlated with glioblastoma and pancreatic cancer aggressiveness." (PMID 36831562, 2023). "High expression of stromal signature genes, such as COL3A1, is correlated with poor prognosis in glioblastoma." (PMID 33816228, 2021). "In glioblastoma, we identified an RND1low signature of six genes (ITGA5, COL3A1, COL5A1, MET, COL1A2, LAMC1), upregulated in glioblastoma patients with low RND1, that predicts the overall survival of glioblastoma patients." (PMID 31344837, 2019). "This study showed modulation of several genes related to cell adhesion and migration, such as CTGF, COL3A1, SERPINE1 and THBS1, all of which we found to be modulated in glioblastoma cells." (PMID 30850678, 2019). "The results obtained in the present study signified the importance of some genes, such as COL3A1, FN1, and MMP9, for glioblastoma." (PMID 28191466, 2017). "Finally, based on signaling pathways activated in patients with low levels of RND1, we identified an RND1low signature of six genes (MET, LAMC1, ITGA5, COL5A1, COL3A1, COL1A2) that is an independent prognostic factor in glioblastoma." (PMID 30333910, 2018).
osteoarthritis (11 papers, 2016 to 2026). A noninflammatory degenerative joint disease occurring chiefly in older persons, characterized by degeneration of the articular cartilage, hypertrophy of bone at the margins and changes in the synovial membrane. "The expression of COL3A1 was associated with the increase of IL-1β in osteoarthritis and was also linked to immune cell infiltration." (PMID 37415178, 2023). "Immune infiltration study confirmed enrichment analysis's finding that COL3A1 could affect the course of osteoarthritis by controlling immunological pathways." (PMID 41685314, 2026). "Additionally, osteoarthritis synovia contained a significantly lower ratio of COL3A1+ Mp (0.46 ± 0.07) when compared with RA synovia (lymphoid type) (p < 0.01)." (PMID 38601143, 2024). "Previous studies have shown that COL3A1 is increased in osteoarthritic cartilage compared to normal cartilage, and its expression may correlate with the radiographic severity of osteoarthritis." (PMID 35831853, 2022). "First, by principle of serendipity, we found that in LpPRP-untreated joints, in synovitis due to meniscal tears or focal cartilage lesions, destructive peptides such as calgizzarin, COL3A1, and COL2-1, known to induce cartilage destruction and osteoarthritis, are enhanced." (PMID 37151865, 2023).
aneurysm (10 papers, 2015 to 2025). Bulging or ballooning in an area of an artery secondary to arterial wall weakening. "Pathogenic variants in COL3A1 are associated with vascular-type Ehlers–Danlos syndrome and with aneurysms of the aorta and other arteries (OMIM: 130050)." (PMID 39125885, 2024). "A COL3A1 null mutation p.Arg491X was observed, segregating in patients with aneurysms in one family." (PMID 26017485, 2015). "Most research on COL3A1 genetic variants in humans has focused on associations with Ehlers–Danlos syndrome, but several case studies have reported on patients with pathogenic mutations who are susceptible to aortic or arterial dissections, aneurysms, and ruptures." (PMID 39996803, 2025). "Previous studies in the Col3A1-related vascular Ehlers–Danlos mouse model also show sex-based differences in aneurysm." (PMID 35743192, 2022). "We report for the first time the association of diffuse coronary artery ectasia and aneurysms with a single nucleotide variant of currently classified unknown significance (VUS), p.P517R within exon 22 of the COL3A1 (collagen type III alpha 1 chain) gene." (PMID 39996803, 2025). "In addition, the miR-29 family is involved in aneurysm development by mediating extracellular matrix protein synthesis, including Col1a1, Col3a1, Col5a1, and Eln." (PMID 28164126, 2017). "In murine models of abdominal aortic aneurysms, miR-29b-3p upregulation accelerated aneurysm expansion and increased rupture rates, accompanied by decreased expression of key ECM targets (e.g., Col1a1, Col3a1, Col5a1, and Eln), while inhibition of miR-29b-3p reduced aortic aneurysm progression." (PMID 39767655, 2024).
melanoma (10 papers, 2021 to 2025). A malignant, usually aggressive tumor composed of atypical, neoplastic melanocytes. "Melanoma is usually considered as a “hot” tumour, but some specific gene mutations such as COL3A1, EGFR, etc. can lead to decreased immune infiltration or increased immune checkpoints in TME." (PMID 39530091, 2024). "A study of 631 melanoma patients who received blockade therapy of immune checkpoints showed that patients with COL3A1 mutations showed a significantly improved OS and PFS compared with patients without such mutations." (PMID 39530091, 2024). "The alterations in COL3A1 have been demonstrated to be associated with melanoma metastasis." (PMID 39530091, 2024). "COL3A1, the extracellular matrix gene, which was first identified as a cause of autosomal dominant Ehlers-Danlos disease, was subsequently reported to be dramatically changed in individuals with melanoma." (PMID 36059672, 2022). "We evaluated the prognostic power of COL3A1 mutations in TCGA melanoma cohort." (PMID 35087523, 2021). "COL3A1 is a member of the fibrillar collagen family that functions in extensible connective tissues such as the skin, and alterations in COL3A1 have been demonstrated to be associated with melanoma metastasis." (PMID 35087523, 2021). "By using the same pooled melanoma and NSCLC cohorts, we also discovered other mutations of the genes FAT1, COL3A1, NRAS, NARS2, DCC, and PTPRT were associated with better ICI response and outcome." (PMID 35884556, 2022). "Many of these downregulated proteomic cargoes in melanoma sEVs, including collagens (COL1A1, COL3A1, COL6A1–A3, and COL14A1), matrix-associated proteoglycans (DCN, LUM, FMOD, OGN, and PRELP), and structural regulators (TNXB and PCOLCE), are key components of ECM organization and tensile strength." (PMID 41271007, 2025). "In this study, we also observed that melanoma patients with and without COL3A1 mutations exhibited a survival difference in the setting of anti-CTLA-4 therapy, but not in the anti-PD-1/PD-L1 therapy." (PMID 35087523, 2021). "The non-immune cell clusters were made up of melanoma cells (MLANA, PMEL, MITF, DCT), endothelial cells (VWF, PECAM1) and fibroblast cells (COL1A1, COL3A1)." (PMID 36433984, 2022).
myocardial infarction (10 papers, 2009 to 2025). Gross necrosis of the myocardium, as a result of interruption of the blood supply to the area, as in coronary thrombosis. "COL3A1 encodes a fibrillary collagen molecule that has been linked to myocardial infarction and the risk of stroke recurrence and prognosis in Chinese patients." (PMID 27655637, 2016). "miR‐30a has been shown to attenuate cardiac fibrosis in myocardial infarction rats by reducing the Col1a1/Col3a1 ratio." (PMID 39592912, 2025). "Previous studies have shown that quercetin restrains the level of fibrotic proteins including TGF-β1, α-SMA, Col1a1, and Col3a1 in heart tissue of myocardial infarction model." (PMID 38476331, 2024). "MiR-29b and miR-205-3p could downregulate the expression of TGF-β1, Col1a1, and Col3a1, so as to resist MF following myocardial infarction." (PMID 38476331, 2024). "In addition, CAR3 deficiency dampened the mRNA levels of ECM-related genes Col1A1, Col3A1, Postn and Acta2 after myocardial infarction." (PMID 38481818, 2024). "COL1A1 and COL3A1 mRNA as well as collagen cross-linking enzymes were found to be upregulated by the transcription factor Zinc Finger E-Box Binding Homeobox 1 (ZEB1) in the context of myocardial infarction." (PMID 37373151, 2023). "Moreover, TGF-β1 is overexpressed in the heart in a high-cholesterol-fed porcine model of myocardial infarction, and its downstream Smad2 and Smad3 are activated, thereby increasing collagen synthesis and the levels of Col1a1, Col3a1, and α-SMA." (PMID 34485393, 2021). "Another study in mice demonstrated that gene expression of fibroblasts was skewed toward Ki-67, COL1A2, collagen type III alpha 1 chain (COL3A1), collagen type V alpha 1 chain (COL5A1), SPARC, secreted frizzled related protein 2 (SFRP2), and DKK3 following myocardial infarction." (PMID 35548426, 2022).
pancreatic cancer (10 papers, 2006 to 2025). "This reduced overall survival demonstrates the importance of COL3A1 expression in pancreatic cancer prognosis." (PMID 36415513, 2022). "CAFs were one of the most abundant cell types identified in pancreatic cancer TME and robustly expressed markers such as Pdgfra, Col3a1 and Dcn." (PMID 37954069, 2023). "Desmoplasia has a crucial role in drug resistance and the progression of pancreatic cancer, and a study identified that a combination of gemcitabine and EC359 affected desmoplasia by down-regulating COL3A1." (PMID 36415513, 2022). "We further analyzed the overall survival of COL3A1, FN1 and ITGA2 in pancreatic cancer and normal tissues." (PMID 34461940, 2021). "In addition, the protein levels of COL3A1, FN1 and ITGA2 in pancreatic cancer were improved according to HPA." (PMID 34461940, 2021).
prostate carcinoma (10 papers, 2012 to 2025). A carcinoma that arises from epithelial cells of the prostate gland. "Module 2 includes COL3A1, COL5A2, and NOTCH3, which have been reported to be associated with metastasis in prostate cancer, as well as HEYL, STMN2, and ASPN, which have been implicated in prostate cancer progression." (PMID 39347576, 2024). "Collagen type III alpha 1 chain (COL3A1) has been identified as the main mediator of RNF185’s ability to promote the migration phenotype in prostate cancer cells as COL3A1 inhibition was capable of attenuating the migration and metastasis of the cancer cells." (PMID 38139010, 2023). "The COL3A1, one of the 93 stroma-derived metastasis signature genes, was identified from the metastatic primary prostate cancer." (PMID 36232736, 2022). "Result showed that COL3A1 and SDC2 were found to be the highest risk factors of prostate cancer, followed by RAC1 and PTPRF." (PMID 34229299, 2021). "The means of the gene expression level of COL1A1 in prostate cancer tissue in GS 3 + 3, 3 + 4, 4 + 3, 3 + 5, and 4 + 5 were 383, 920.6, 2729, and 927, respectively, while in COL3A1 they were 48.6, 114.2, 198.5, and 163.7, respectively." (PMID 34771715, 2021). "Furthermore, the existence of these EMP1+/COL3A1+ fibroblasts was also verified in prostate cancer and renal cancer BoM samples, suggesting the importance of these fibroblasts from a pan-cancer perspective." (PMID 38187400, 2023). "Thus, the replenishment of RNF185 or the targeting of COL3A1 may be considered as possible strategies for prostate cancer therapy." (PMID 38139010, 2023). "Differences in collagen content, orientation, distribution, structures, and type play a critical role in prostate cancer progression, demonstrating, by gene expression, that the amount of COL1A1 increased in cancer tissue compared to COL3A1." (PMID 37894275, 2023). "Among different subgroups in prostate cancer scRNAseq data, significant correlations between EMP1/COL3A1 and four EMT genes (VIM, SNAI2, TWIST1, and CTNNB1) were found in the osteoblast subgroup." (PMID 38187400, 2023). "Furthermore, there was a significant correlation between COL3A1 and EMP1 in osteoblasts, suggesting the enrichment of COL3A1+/EMP1+ cells during the BoM process in prostate cancer." (PMID 38187400, 2023). "In prostate cancer, more EMP1+/COL3A1+ osteoblasts were found instead of fibroblasts." (PMID 38187400, 2023). "Our results revealed that COL3A1, SDC2 and FN1 are dramatically enriched in the ECM-receptor interaction pathway, which may play a key role in the process of tumor development and bone metastasis of prostate cancer." (PMID 34229299, 2021).
Hypertension (9 papers, 2019 to 2025). The presence of chronic increased pressure in the systemic arterial system. "It is worth noting that in our study, patient #54 with three VUSs (in genes FBN1, COL3A1, and PLOD3) has only one CVD risk factor: arterial hypertension." (PMID 39125885, 2024). "Enrichment analysis of DMGMs showed that the COL3A1 module was related to 21 biological processes and 8 diseases, focused on regulation of blood pressure and cardiovascular and hypertensive diseases." (PMID 38530405, 2024). "Additionally, this study found that fibrotic markers Col1a1, Col3a1, and Fn1, as well as renal interstitial fibrosis, were significantly reduced following macrophage depletion in existing hypertension." (PMID 41175639, 2025). "Upregulation of Col3a1 and other ECM regulators in the vascular wall is a key part of the cerebrovascular adaptive response to hypertension." (PMID 38425784, 2024). "In our present study, DF treatment and exercise significantly reduced the expression of fibrotic protein markers such as uPA, CTGF, COL1A1, and COL3A1, as well as hypertrophy markers such as NFATC3, GATA4, BNP, and ANP, which indicates that it could attenuate hypertension-mediated myocardial injury." (PMID 35890118, 2022).
triple-negative breast carcinoma (9 papers, 2020 to 2025). An invasive breast carcinoma which is negative for expression of estrogen receptor (ER), progesterone receptor (PR), and human epidermal growth factor receptor 2 (HER2). "Additionally, in triple-negative breast cancer, COL3A1 suppression causes a decrease in PD-L1 expression and subsequently inhibits cancer cell proliferation and metastasis." (PMID 39761856, 2025). "For example, Yuee Teng’s team found that METTL3 downregulated the expression of COL3A1 by increasing the m6A abundance on COL3A1 mRNA and thus inhibited the metastasis of triple-negative breast cancer cells." (PMID 35945641, 2022). "Methyltransferase-like 3 could suppress the expression of COL3A1 by upregulating its m6A methylation, ultimately inhibiting the metastasis of triple-negative breast cancer cells." (PMID 35047627, 2021). "In triple-negative breast cancer (TNBC), METTL3 expression was relatively low; restoring METTL3 increased m6A on the COL3A1 mRNA, which led to reduced COL3A1 expression and impaired invasion." (PMID 41301491, 2025). "Another study found that METTL3 decreases Collagen type III alpha 1 chain (COL3A1), thus inhibiting triple-negative breast cancer (TNBC) cell metastasis." (PMID 36008936, 2022). "Collagen subunit proteins COL1A1, COL1A2, COL3A1, and COL11A1 have been related to triple-negative breast cancer: COL1A1 expression is elevated in TNBC tissues and is associated with increased tumor stiffness, promoting cancer progression and metastasis, making it an independent prognostic factor." (PMID 40867231, 2025).
COVID-19 (8 papers, 2022 to 2025). A disease caused by infection with severe acute respiratory syndrome coronavirus 2. "In our study, some markers of the intussusceptive vascular remodeling typical for COVID-19 were upregulated during the acute (Ccl12, Gdf15, and Cd163) or chronic phase (Col3a1, Cxcl12)." (PMID 40021627, 2025). "In fact, overexpression of some genes involved in these processes, such as COL1A2 and COL3A1, were observed in both COVID-19 and UIP/IPF." (PMID 36405615, 2022). "COL3A1 is a well-characterized marker of late MT that is increased in COVID-19 patients." (PMID 36248845, 2022). "COL3A1 expression was increased in COVID-19 compared to controls, and although all GSE statistics of MMP2-positive cells were not significant, MMP2-positive cells were statistically differentially upregulated in late stage of EndMT by meta-analysis of GSE data." (PMID 36248845, 2022). "Using meta-analysis, we demonstrated that the MMP2 pooled SMD in 5 distinct GEO datasets was 0.54, 95% CI (0.13.0.96), and ultimately, meta-analysis revealed that the COL3A1 pooled SMD of late stages of COVID-19 was 0.84, 95% CI (0.24,1.44) when compared to controls." (PMID 36248845, 2022). "Specifically, signatures of plasma cells (IGHG3, IGKC, IGHM, JCHAIN, IGHG2, IGKV4-1, IGLV3-1, IGHA1), activated fibroblasts (COL1A1, COL1A2, COL3A1), inflammatory cytokines (CXCL9, CCL18) and complement factors (C1QB, C1QC) dominated the DE genes for the COVID-19 lung sections." (PMID 37858234, 2023).
leiomyoma (8 papers, 2008 to 2026). A well-circumscribed benign smooth muscle neoplasm characterized by the presence of spindle cells with cigar-shaped nuclei, interlacing fascicles, and a whorled pattern. "COL1A1 and COL3A1 expression levels were downregulated after inhibition of UCHL1 in human leiomyoma cells." (PMID 36830563, 2023). "Collagen 3A1 (COL3A1) template demonstrated an up-regulation of gene expression (1·99 ± 0·39; P < 0·05) in untreated leiomyomas compared to myometrial cells." (PMID 18248652, 2008). "In addition, the expression of MIAT correlated with the MED12 mutation status of the leiomyomas, and knock down of MIAT in leiomyoma smooth muscle cells’ spheroids blocked the effects of TGF-β3 on the induction of COL1A1 and COL3A1 expression." (PMID 38279317, 2024). "The expression of COL1A1 and COL3A1 significantly decreased in leiomyoma cells." (PMID 36830563, 2023). "Fib-EXO increased the expression of vimentin, EZH2, DNMT1, TGF-β3, and c-MYC, and phosphorylated p65 protein, reduced COL1A1 and COL3A1 expression, and decreased miR-133a, miR-29, and miR-200c while increasing miR-21 in cultured myometrial smooth muscle cells, mirroring changes observed in fibroids." (PMID 42008339, 2026). "To explore the effect of UCHL1 silencing and inhibition in leiomyoma and myometrial cells, we detected the expression of COL1A1 and COL3A1 mRNA using quantitative real-time PCR." (PMID 36830563, 2023). "To explore the effects of UCHL1 knockdown and inhibition in leiomyoma and myometrial cells, we determined the mRNA expressions of COL1A1 and COL3A1." (PMID 36830563, 2023). "They identified several proteins up regulated in the leiomyoma: POSTN, TNC, COL3A1, COL24A1, and ASPN." (PMID 31100862, 2019). "In addition, tranilast was recently shown to suppress transcription of COL3A1 and CDK2 through regulation of the microRNA miR-29c in leiomyoma smooth muscle cells." (PMID 29666462, 2018).